C1QB (complement C1q B chain)
Description:
Core component of the complement C1 complex, a multiprotein complex that initiates the classical pathway of the complement system, a cascade of proteins that leads to phagocytosis and breakdown of pathogens and signaling that strengthens the adaptive immune system. The classical complement pathway is initiated by the C1Q subcomplex of the C1 complex, which specifically binds IgG or IgM immunoglobulins complexed with antigens, forming antigen-antibody complexes on the surface of pathogens: C1QA, together with C1QB and C1QC, specifically recognizes and binds the Fc regions of IgG or IgM via its C1q domain. Immunoglobulin-binding activates the proenzyme C1R, which cleaves C1S, initiating the proteolytic cascade of the complement system. The C1Q subcomplex is activated by a hexamer of IgG complexed with antigens, while it is activated by a pentameric IgM. The C1Q subcomplex also recognizes and binds phosphatidylserine exposed on the surface of cells undergoing programmed cell death, possibly promoting activation of the complement system.
Synonyms: C1QD2
Gene: Protein-coding gene on chromosome 1 (22,652,713 to 22,661,637, forward strand). Ensembl gene ENSG00000173369.
Subcellular location: Secreted; Cell surface
Pathways (Reactome):
Immune System: Classical antibody-mediated complement activation; Initial triggering of complement; Regulation of Complement cascade
Genetic constraint (gnomAD): Loss-of-function variants: 4 observed, 9.14 expected, observed/expected ratio (o/e) 0.44, 90% interval 0.21 to 1. That is too few expected variants to judge how well the gene tolerates losing a copy. Missense variants: 292 observed, 356.09 expected, observed/expected ratio (o/e) 0.82, 90% interval 0.74 to 0.9. Synonymous variants: 132 observed, 145.21 expected, observed/expected ratio (o/e) 0.91, 90% interval 0.79 to 1.05.
Gene-disease validity (ClinGen):
ClinGen rates the evidence that C1QB causes each of these diseases.
C1Q deficiency (autosomal recessive): Definitive. C1q deficiency is a rare disorder associated with recurrent skin lesions, chronic infections, systemic lupus erythematosus (SLE) or SLE-like diseases.
Homologues: Orthologues: chimpanzee C1QB (99% identical), macaque C1QB (95% identical), dog C1QB (84% identical), mouse C1qb (80% identical), guinea pig C1QB (79% identical), rat C1qb (78% identical), rabbit C1QB (78% identical), pig C1QB (67% identical), tropical clawed frog C1QB (56% identical). Paralogues in human: C1QC (49% identical), C1QA (39% identical), C1QTNF9 (37% identical), C1QTNF9B (36% identical), COL10A1 (35% identical), C1QTNF2 (35% identical), COL8A1 (35% identical), COL8A2 (34% identical), C1QTNF7 (34% identical), C1QTNF5 (33% identical), ADIPOQ (32% identical), C1QL2 (31% identical), and 11 more.
Diseases named in the same sentence as C1QB in open-access papers:
C1QB is named in the same sentence as 137 diseases in open-access papers, as found by Europe PMC text mining. Sharing a sentence is not in itself a finding about the gene and the disease. The quoted sentences say what the papers report.
COVID-19 (16 papers, 2020 to 2025). A disease caused by infection with severe acute respiratory syndrome coronavirus 2. "Patients with devere and mild COVID-19 exhibited substantial reduction in the expression of FABP4, APOC1, APOE, C1QB, and NURP1, all associated with interstitial and macrophage cluster-0." (PMID 33138195, 2020). "Based on our data and previous research, increased expression of C1QA and C1QB could to be involved in pathogenesis and lethality of COVID-19, and could be considered a molecular marker of milder cases, and stimulation of their expression could be a possible option for therapeutic intervention." (PMID 40374692, 2025). "On the other hand, the Humoral response GO term, reflecting both complement (SERPING1, C1QB) and B cell activation (JCHAIN, POU2AF1), was progressively more enriched in COVID-19 patients from T1 through T3." (PMID 37365222, 2023). "The identification of key immune-modulating genes like ISG15, SERPING1, C1QA, C1QB, and VSIG4 opens avenues for therapeutic approaches that aim to modulate the immune response and improve outcomes in severe COVID-19 cases via upregulation of expression of these genes." (PMID 40374692, 2025). "Similarly, in previous reports, FGB, FGG, complements C4, C3, C5, C2, C9, and complement C1q subcomponent subunits A, B, and C (C1QA, C1QB and C1QC) were found to be upregulated in the lung tissues of patient with COVID-19." (PMID 38882332, 2024). "Nasal macrophages had several differentially expressed (DE) genes in patients with COVID-19 versus patients with LRTD that mirrored alveolar macrophage responses (SPP1, LGALS1 and TMSB10), including IFN-γ response genes (HLA-DPB1, HLA-DQA1 and C1QB)." (PMID 39567718, 2024). "Of note, we observed a localized downregulation of certain complement factors (C1QB, CFD, and C7) and interferon response genes (IFI6 and ISG15), in contrast to their enrichment in COVID-19 lungs compared to control lungs in our samples and in others analyzed in previous works." (PMID 37858234, 2023). "Specifically, signatures of plasma cells (IGHG3, IGKC, IGHM, JCHAIN, IGHG2, IGKV4-1, IGLV3-1, IGHA1), activated fibroblasts (COL1A1, COL1A2, COL3A1), inflammatory cytokines (CXCL9, CCL18) and complement factors (C1QB, C1QC) dominated the DE genes for the COVID-19 lung sections." (PMID 37858234, 2023). "Of note, the complement genes C1QA and C1QB that show elevated expression in nonclassical monocytes from COVID-19 patients are preferentially expressed in BA.2 patients." (PMID 35441161, 2022). "Interestingly, although macrophages were also present in healthy subjects and patients with mild COVID-19, they had different gene signatures, indicative of interstitial and cluster-0 macrophage (i.e., FABP4, APOC1, APOE, C1QB, and NURP1)." (PMID 33138195, 2020).
melanoma (14 papers, 2011 to 2025). A malignant, usually aggressive tumor composed of atypical, neoplastic melanocytes. "However, MR analysis revealed that targeted inhibition of C1QB may increase the risk of ovarian cancer and melanoma." (PMID 39109334, 2024). "Cd74/C1q/Aif1-expressing macrophages also are characterized by higher expression of the complement components C1qa and C1qb, which have been positively correlated with immune cell infiltration, apoptosis, and improved survival in previous studies of melanoma." (PMID 41122966, 2025). "TREM2+ TAMs from ESCC exhibited a consistent expression pattern and identical signature genes (TREM2, SPP1, APOE, C1QC, C1QB, and C1QA) with melanoma cells, suggesting that TREM2+ TAMs were associated with immunotherapy resistance in ESCC." (PMID 37187751, 2023). "And significant differences of C1QA and C1QB expressions were found in T stage, pathologic stage, melanoma ulceration, melanoma Clark level, and Breslow depth (P < 0.05)." (PMID 36443341, 2022). "Compared to nevus and normal samples, significant higher expressions of GZMB, C1QA, and C1QB were observed in primary melanoma and metastatic melanoma in GSE46517." (PMID 36443341, 2022). "The outcomes indicated that knockdown of C1QB prominently dampened the proliferative, migratory and invasive abilities of melanoma cells, but accelerated melanoma cell apoptosis." (PMID 34915882, 2021). "To conclude, these findings demonstrated that C1QB promoted proliferation, migration and invasion of melanoma cells, while inhibiting the cell apoptosis." (PMID 34915882, 2021). "The collected data indicated that C1QB was expressed at a higher level in melanoma cells, in contrast to HEMa-LP cells." (PMID 34915882, 2021). "In summary, our study mainly illustrated the role of IRF4/TEX41/miR-103a-3p/C1QB axis in melanoma cells." (PMID 34915882, 2021). "In this study, functional experiments revealed that down-regulation of C1QB inhibited melanoma cell proliferation, migration, invasion while promoting cell apoptosis." (PMID 34915882, 2021). "Of these, a 2-gene signature consisting of PLEK2 and C1QB led to the best result that correctly classified 93.3% melanoma patients and 90% healthy controls." (PMID 21698244, 2011). "On the other hand, C1QB was upregulated in CD45+ subset in melanoma patients from all stages compared with healthy individuals." (PMID 21698244, 2011). "In the current study, we found that C1QB expression was significantly increased in the leukocytes of melanoma patients from all stages." (PMID 21698244, 2011). "Furthermore, in malignant melanoma, C1QB promotes proliferation, migration, and invasion, while inhibiting cell apoptosis, and the high-expression group exhibits significant enrichment of genes related to immune and apoptosis." (PMID 38980810, 2024). "C1QB is the diagnostic and prognostic biomarker for skin cutaneous melanoma patients, IRF4 could promote melanoma cell growth via upregulating C1QB." (PMID 37071001, 2023). "Recent studies announced C1QB as a strong biomarker for the classification of CM patients, which could be utilized for both early discovery of melanoma and follow-up monitoring of patients.." (PMID 35300397, 2022). "Nonetheless, the underlying mechanism of C1QB in affecting biological behaviors of melanoma cells has not been discussed in this study, which will be the focus of our future study." (PMID 34915882, 2021). "Up-regulation of C1QB has been reported in PBMCs of melanoma patients." (PMID 33782087, 2021). "It has also been reported that C1QB is high-expressed in stage I and II melanoma patient samples." (PMID 34915882, 2021). "Then, we performed qRT-PCR to detect the expression of C1QB in HEMa-LP and melanoma cells." (PMID 34915882, 2021). "In brief, IRF4 raised C1QB expression in melanoma cells to facilitate cell growth." (PMID 34915882, 2021).
melanoma (continued). "It is possible that PLEK2 and C1QB may belong to independent pathways; therefore, changes in expression of both genes may increase reliability in detecting melanoma patients." (PMID 21698244, 2011). "However, the function of C1QB in melanoma remains unexplored." (PMID 34915882, 2021). "Our findings will help reveal the multifaceted roles of C1QA, C1QB, and C1QC and provide evidence for future immunotherapy of melanoma." (PMID 36110204, 2022). "Furthermore, IRF4 could modulate C1QB to affect melanoma cell growth." (PMID 34915882, 2021). "Prior to the exploration on the function of C1QB in melanoma cells, we first searched on GEPIA database to find the expression of C1QB in SKCM tissues and normal skin tissues." (PMID 34915882, 2021). "As a miR-103a-3p sponge and C1QB modulator, TEX41 promoted proliferation, migration and invasion of melanoma cells while repressing cell apoptosis." (PMID 34915882, 2021). "Moreover, IRF4 could facilitate melanoma cell growth via up-regulating C1QB." (PMID 34915882, 2021). "C1QB, CXCL9, CXCL10, DFNA5 (GSDME), FCGR1B, and PRAME were increased in melanoma, and SCGB1D2 was decreased in melanoma, compared to dysplastic nevi or nevi that progressed to melanoma." (PMID 35008167, 2021). "Further analysis of C1QB, PLEK2 and the other validated biomarkers in fractionated blood cells will provide us more insight into their functions and roles in melanoma development and progression." (PMID 21698244, 2011). "IRF4-activated TEX41 sequestered miR-103a-3p and modulated C1QB to promote melanoma cell malignant behaviors, for which TEX41 might be regarded as a potential therapeutic target for melanoma." (PMID 34915882, 2021). "Rescue experiments further validated that overexpression of C1QB could counteract the effects of TEX41 depletion on the proliferation, migration, invasion and apoptosis of melanoma cells." (PMID 34915882, 2021). "Furthermore, we found that melanoma conditioned medium induced upregulation of C1QB in CD45+ cells (data not shown)." (PMID 21698244, 2011). "We focused on macrophages and identified TREM2+ TAMs specifically expressing TREM2, SPP1, APOE, C1QC, C1QB, and C1QA, which were significantly upregulated in melanomas not responsive to ICB therapy." (PMID 37187751, 2023).
osteosarcoma (11 papers, 2021 to 2024). A usually aggressive malignant bone-forming mesenchymal neoplasm, predominantly affecting adolescents and young adults. "Thus, C1QA and C1QB may be implicated in the pathogenesis and metastasis of osteosarcoma, and the underlying mechanisms may rely on regulating macrophage polarization in osteosarcoma." (PMID 38256356, 2024). "One study has reported that an osteosarcoma patient with high C1QB expression tended to have a favorable outcome and that C1QB expression was correlated with the percent necrosis observed at definitive surgery." (PMID 36313902, 2022). "C1QB expression has been reported in the tumor microenvironment of multiple cancers, such as ovarian cancer, prostate cancer, glioma, and osteosarcoma." (PMID 36313902, 2022). "C1QA and C1QB might be potential prognostic factors and indices of tumor microenvironment remodeling in osteosarcoma." (PMID 36247009, 2022). "Moreover, high levels of C1QB expressions were associated with favorable prognosis in basal-like breast cancer, HER2-positive breast cancer, skin cutaneous melanoma patients, and osteosarcoma." (PMID 39109334, 2024). "Additionally, C1QB has been found to exert an impact on the TME and is positively associated with infiltration levels of CD8 + T cell, as well as with M1 and M2 macrophages in osteosarcoma." (PMID 38980810, 2024). "Another study found that C1QB might be a protective factor in osteosarcoma patients." (PMID 36313902, 2022). "In a recent analysis, complement classical pathway genes C1QA, C1QB, C1QC were proved to be protective factors for survival in osteosarcoma." (PMID 35493104, 2022). "C1qb, a known component of the complement shown to be positively correlated with macrophages and CD8+ cells in osteosarcoma, was significantly upregulated in the ConA+Veh group when compared to the Naïve and was downregulated with TCDD treatment." (PMID 35720411, 2022). "The differential expressions of C1QA, C1QB and C1QC were found to be closely related to the survival prognosis, pathological features, and tumor microenvironment of osteosarcoma, which can help improve the clinical prognosis and immunotherapy." (PMID 35765947, 2022). "However, the immunomodulatory mechanism and actions of C1qA, C1qB and C1qC in osteosarcoma are not clear." (PMID 34079754, 2021).
glioma (10 papers, 2019 to 2024). A benign or malignant brain and spinal cord tumor that arises from glial cells (astrocytes, oligodendrocytes, ependymal cells). "We, therefore, performed a bioinformatics analysis, using Oncomine dataset and UALCAN database in order to assess whether the expression of the genes encoding for the three chains of C1q (C1qA, C1qB, and C1qC) could serve as a potential prognostic marker for gliomas." (PMID 31649675, 2019). "As a result of C activation, high expression of C1QA, C1QB, and C1QC, encoding the three chains of C1q, were observed in gliomas." (PMID 37174113, 2023). "Similarly, a glioma-related study found that expression of C1QB mRNA was negatively related to the survival rate in patients with grade III glioma and glioblastoma." (PMID 36313902, 2022). "Previous studies have shown that C1q, the first recognition subcomponent of the complement classical pathway, comprises three chains (C1qA, C1qB, and C1qC) and exerts complex effects on tumorigenesis of multiple tumors, including prostate, and ovarian cancer as well as gliomas." (PMID 33014868, 2020). "C1qA, C1qB, and C1qC expression in gliomas in the datasets used in the current study with Oncomine." (PMID 31649675, 2019). "According to the latest studies, the expression of C1QB was upregulated in CCRCC patients, glioma patients, gastric cancer patients, CRC patients, PRCC, and breast cancer." (PMID 39109334, 2024). "Moreover, we found that both C1QB and FCER1G had the highest expression levels in GBMs, as well as the lowest expression levels in normal brain tissue, and that the expression levels of C1QB and FCER1G were positively correlated with glioma grades." (PMID 32091665, 2020). "And there was a negative correlation between higher levels of C1QB expression and unfavorable prognosis of patients with CCRCC, lung adenocarcinoma, glioma patients, and gastric cancer patients." (PMID 39109334, 2024).
breast carcinoma (7 papers, 2011 to 2024). "Bandini also confirmed that C1qA, C1qB and C1qC expression levels were positively linked to a good prognosis in breast cancer patients using in vivo investigation of C1q-deficient mice." (PMID 34079754, 2021). "Only C1QB mRNA expression was negatively associated with high DFS and OS rates in the breast cancer patients with luminal-A, and to a DFS rate with all breast cancer." (PMID 31130944, 2019). "Deficiency of C1q has been associated with autoimmune diseases such as lupus erythematosus and glomerulonephritis, and upregulation of C1QB was reported in infiltrating immune cells of stomach and breast carcinoma and in the brain of COX-2 transgenic mice." (PMID 21698244, 2011). "Our results showed that C1QB was not significantly differentially expressed in breast cancer and normal samples." (PMID 34055036, 2021).
lung carcinoma (7 papers, 2019 to 2025). "In contrast, C1QC+ TAMs expressed the classical TAM-associated genes C1QA, C1QB, C1QC, APOE, and TREM2, which were previously reported in lung cancer." (PMID 37383234, 2023). "A previous study found that overexpression of the C1QB protein was correlated with lymph node metastasis of lung cancer." (PMID 36969247, 2023). "In contrast, TAM-like macrophages expressed a set of genes (APOE, C1QA, C1QB and TREM2), which was found previously to be expressed in the TAMs of lung cancer." (PMID 36466840, 2022). "On the other hand, lower levels of the C1QB, C3 and C4BPA proteins have been detected in lung cancer tissues than in normal lung tissues." (PMID 30841875, 2019). "On one hand, higher levels of the complement proteins C1QB, C3 and C4BPA were detected in plasma from patients with lung cancer than in healthy subjects." (PMID 30841875, 2019). "Microarray-based transcriptome profiles revealed lower levels of the C1QB, C3 and C4BPA mRNAs in lung cancer tissues than in healthy tissues." (PMID 30841875, 2019). "Furthermore, we observed a significant increase in expression of C1QB and C1QC in macrophages in KRASG12D-driven, but not non–KRAS-driven, lung cancer, recapitulating our findings in the L-iKRAS model." (PMID 39782689, 2025).
atherosclerosis (6 papers, 2020 to 2025). A disease characterized by the build-up of fatty material and calcium deposition in the arterial wall resulting in partial or complete occlusion of the arterial lumen. "The dual role of C1qB in atherosclerosis—both promoting inflammation and providing protective effects—highlights its complexity in disease progression." (PMID 40607379, 2025). "C1QB is a polypeptide chain of the serum complement subcomponent C1q, and the effects of C1q on the nervous system and atherosclerosis have already been described earlier." (PMID 39188714, 2024). "Finally, the C1QB and C1QA genes regulate the development of atherosclerosis by activating the complement system." (PMID 41348730, 2025). "In the atherosclerosis dataset GSE28829, CD14 (AUC = 0.938), C1QB (AUC = 0.947), CD53 (AUC = 0.952), LY96 (AUC = 0.904), P2RX7 (AUC = 0.981), C3 (AUC = 0.817), and TNFSF13B (AUC = 0.875) demonstrated favorable diagnostic efficiency for differentiating patients with atherosclerosis from controls." (PMID 37649719, 2023). "In this study, we suggested that the progression of atherosclerosis might be related to CD86, C1QB, CD53, C1QC, NCF2, and ITGAM and that it plays a role in regulating immune-competent cells such as T cell CD8 and macrophages M0 and M2." (PMID 32821283, 2020).